APOBEC3B (apolipoprotein B mRNA editing enzyme catalytic subunit 3B)
Diseases named in the same sentence as APOBEC3B in open-access papers (continued):
Sharing a sentence is not in itself a finding about the gene and the disease.
breast cancer (continued). "In addition, specific mutation signals and the role of APOBEC3B, as a cytidine deaminase, have been established in the occurrence and development of cervical cancer, breast cancer, lung cancer, and other cancers." (PMID 36203448, 2022). "Several reports showed that higher levels of APOBEC3B expression was associated with decreased survival rates among estrogen receptor-positive (ER+) breast cancer patients and a higher expression of APOBEC3B was independently associated with lower survival rates of ovarian cancer patients." (PMID 32934779, 2020). "In addition, we recently reported higher mRNA levels of APOBEC3B in breast cancer metastasis as compared to the corresponding primary tumor, which implied that breast cancer progression is associated with the upregulation of APOBEC3B." (PMID 31357602, 2019). "APOBEC3B mutation signature is specifically enriched (C to T transition) in six types of cancers, including cervix, bladder, lung (adeno and squamous cell), head and neck, and breast cancers." (PMID 30093965, 2018). "APOBEC3B expression is upregulated in breast cancer and is associated with total mutation burden." (PMID 29435122, 2018). "Consequently, meta-analysis in the general population showed significant but modest association of the APOBEC3B deletion with breast cancer [OR(95%CI)=1.193(1.055-1.348), p=0.005]." (PMID 29100317, 2017). "It was recently shown that a common large deletion in the APOBEC3 cluster (the APOBEC3B deletion) may increase the risk of breast cancer." (PMID 29100317, 2017). "Besides its role in innate immunity, APOBEC3B has recently been identified as an endogenous source of mutation in breast cancer." (PMID 27552096, 2016). "Homozygosity for the APOBEC3B null allele is associated with a higher incidence of breast cancer." (PMID 27977754, 2016). "This deletion is associated with decreased expression of the APOBEC3B gene in breast cancer cells." (PMID 26920143, 2016). "APOBEC-3B seems to be an enzymatic source of mutation in breast cancer." (PMID 27932948, 2016). "The prevalence of germline APOBEC3B deletion and its association with breast cancer remain unknown in other populations." (PMID 27233495, 2016). "Here we evaluated whether the APOBEC3B deletion polymorphism also associates with clinical outcome of breast cancer." (PMID 27552096, 2016). "However, three independent studies have indicated that homozygosity for the APOBEC3B null allele associates with a higher incidence of breast cancer." (PMID 25848704, 2015). "Finally, genetic knockdown experiments were used to demonstrate that APOBEC3B is responsible for elevated levels of DNA damage and mutation in several breast cancer cell lines." (PMID 25848704, 2015). "It is already clear that APOBEC3B mutagenesis impacts approximately half of all breast cancers and may be responsible for large proportions of mutations in these tumors, ranging from modest to extremely high levels." (PMID 25848704, 2015). "To address whether the APOBEC-mediated mutagenesis in breast tumors is directly induced by the APOBEC3B protein, stratified by CNV of APOBEC3B locus, we further compared the number of mutations per tumor exome in breast cancer tissues." (PMID 26682542, 2015). "Furthermore, APOBEC3B copy number alterations have been shown to be associated with decreased APOBEC3B expression in breast cancer cell lines." (PMID 26097867, 2015). "To determine whether APOBEC3B mRNA expression was associated with clinical outcome in breast cancer, we related log-transformed values of APOBEC3B using Cox regression analysis with DFS, MFS, and OS." (PMID 25123150, 2014).
breast cancer (continued). "Finally, recent sequencing meta-analyses data have underscored the importance of APOBEC3B in causing both the dispersed and clustered mutations in breast cancer and also implicated it as a dominant mutagen in several additional cancers." (PMID 25123150, 2014). "Earlier work analyzed the germline DNA of breast cancer cases versus healthy controls and reported that a deletion allele of APOBEC3B may be related to a higher incidence of developing breast cancer." (PMID 25123150, 2014). "Moreover, they showed that APOBEC3B was highly expressed in breast cancer cell lines, and that APOBEC3B and APOBEC3A can also cause DNA damage in human cells." (PMID 23599896, 2013). "APOBEC3B encodes a cytosine deaminase that functions in localised hypermutation (“kataegis”) and may be responsible for chronic DNA damage in breast cancers." (PMID 24025454, 2013). "APOBEC3A and APOBEC3B have been linked to persistent cell evolution and therapy resistance in lung cancers, and APOBEC3B has been linked to resistance against androgen receptor (AR)-targeted therapy and Tamoxifen in prostate and estrogen receptor-positive (ER+) breast cancers." (PMID 38254863, 2024). "Furthermore, clinical investigations show that the higher expression of APOBEC3B is associated with a poorer survival rate for estrogen receptor-positive breast cancer patients, which includes brief periods of disease-free survival and, in particular, survival post-surgery." (PMID 36832196, 2023). "In addition, APOBEC3B may contribute to canceration and progression of breast cancer due to accumulation of mutations." (PMID 30093965, 2018). "APOBEC-3B may preferentially edit genomic DNA and is implicated in cancer as its expression correlates with increased DNA damage and thus represents an enzymatic source of mutation in breast cancer." (PMID 27932948, 2016). "Furthermore, the biology is complicated by the existence of a common human germline deletion polymorphism in APOBEC3B, which eliminates the entire coding region of this gene but is paradoxically associated with an increased risk of breast cancer and an increased burden of APOBEC-pattern mutations." (PMID 27716362, 2016). "Meanwhile, we observed that breast cancers in carriers of germline deletion of APOBEC3B gene harbor similar mutation patterns, but higher mutation rates in the TCW motif (W corresponds to A or T) than cancers in non-carriers, indicating additional factors may also induce carcinogenic mutagenesis." (PMID 26682542, 2015). "We addressed whether APOBEC3B is associated with breast cancer clinical outcomes." (PMID 25123150, 2014). "Related studies indicate that the detection of the DNA cytidine deaminase APOBEC3B in breast cancer and the influence of carcinogenic HPV on the expression of this enzyme have largely addressed such doubts." (PMID 41602431, 2026). "In breast tissue, HPV plays a role in the early stage of the disease, and its induction of apolipoprotein B mRNA-editing enzyme catalytic polypeptide-like 3B (APOBEC3B) can lead to genomic instability, thereby inducing breast cancer development." (PMID 41602431, 2026). "APOBEC3B is known to promote tamoxifen resistance in estrogen receptor-positive (ER+) breast cancer patients." (PMID 41373684, 2025). "In particular, breast cancer patients with APOBEC-rich features exhibit higher mutational loads and APOBEC3B protein levels compared to other tumors, and A3B is also associated with a hypermutated phenotype." (PMID 40356722, 2025). "Our recent study revealed that APOBEC3B is upregulated during the preinvasive stages of non-small cell lung cancer and breast cancer." (PMID 38116246, 2023). "Greater estrogen receptor activation (ER) is a likely mechanism since APOBEC3B has been shown to promote ER overexpression in breast cancer." (PMID 36978147, 2023).
breast cancer (continued). "First, we screened the entire APOBEC3B gene in 617 Polish families with hereditary breast cancer by whole exome sequencing and identified a truncating founder mutation c.783delG (p.Val262Phefs)." (PMID 37510234, 2023). "APOBEC3B expression is regulated by estrogen, a hormone critical in the pathogenesis of breast cancer." (PMID 37510234, 2023). "In ER+ breast cancer, high APOBEC3B expression can predict resistance to the endocrine therapy tamoxifen." (PMID 36978147, 2023). "Supporting this approach, APOBEC3B induction has been shown to increase responsiveness to immune checkpoint blockade therapy in mouse models of melanoma and breast cancer." (PMID 36978147, 2023). "For example, APOBEC3B has been shown to drive estrogen receptor (ER) overexpression in breast cancer through transient chromatin remodeling." (PMID 36978147, 2023). "Studies have found that TFF1, one of the downregulated genes in the A3Bhigh group, was regulated by APOBEC3B in breast cancers." (PMID 36249021, 2022). "Our results with APOBEC3D likely indicate a parallel with APOBEC3B in breast cancer, a mutagenic activity of APOBEC3D in CRCs, and suggest survival benefit with a specific inhibitor of APOBEC3D." (PMID 35817785, 2022). "Bladder, cervical, lung squamous cell carcinoma, lung adenocarcinoma, head and neck cancers and breast cancers bear the most elevated APOBEC3B expressions among 19 different cancer types compared to wild type tissue samples." (PMID 36405752, 2022). "In particular, APOBEC3B has been shown to be a prognostic marker in estrogen receptor (ER)+ breast cancer, and that it plays a key role in the progression of breast cancer." (PMID 36203448, 2022). "For example, human papilloma viruses appear to exert an indirect influence on breast cancer by inhibiting the virus protective functions of the APOBEC3B enzymes." (PMID 35458452, 2022). "APOBEC3A and APOBEC3B expression can be induced by interferons, but this has been reported to be limited in urothelial cancer cell lines as compared to breast cancer lines." (PMID 35194151, 2022). "APOBEC3B is involved in the development and progression of breast cancers, hepatocellular carcinomas, ovarian cancers, nasopharyngeal carcinomas, and chondrosarcomas." (PMID 35918642, 2022). "Previous studies reported the deletion of APOBEC3B influenced the immune activation in Asian women with breast cancer." (PMID 34729111, 2021). "Since APOBEC3B is reported to promote breast cancer cell growth depending on the ER status, we analyzed the correlations between the APOBEC signature and success rate of the establishment of the HR+ HER2- PDX model." (PMID 33407601, 2021). "APOBEC3B transcription is increased by an ATR/Chk1-dependent pathway in breast cancer, in addition to viral infection, PMA and interferon-α." (PMID 32880638, 2020). "Two hotspot G-to-A mutations in exon 9 of the—often mutated in breast cancer—PIK3CA gene (E542K and E545K) are thought to be generated by APOBEC3B induced C-to-T (G-to-A) transitions." (PMID 31357602, 2019). "Previous studies reported elevated APOBEC3B mRNA levels in breast cancers with otherwise aggressive characteristics, including high histological grade and lack of estrogen expression." (PMID 31357602, 2019). "Previous studies have proposed that APOBEC3B (A3B) is the major source of mutagenesis in breast cancer (BRCA)." (PMID 31841499, 2019). "Our breast cancer subtype analysis showed that the expression of APOBEC3B was the highest in the ER− subgroup (Mann–Whitney U Test, p = 0.037)." (PMID 31357602, 2019).
breast cancer (continued). "A common germline deletion covering the last intronic of APOBEC3A to the last exon of APOBEC3B (called APOBEC3A/B) is found to increase APOBEC-mutational signature in breast cancer, as a similar pattern driven by the elevated APOBEC3A or APOBEC3B expressions." (PMID 31533728, 2019). "A major role of Apolipoprotein B mRNA Editing Enzyme, Catalytic Polypeptide-Like 3B (APOBEC3B) has been reported in breast cancer and several other cancers." (PMID 31357602, 2019). "Our current data showed that APOBEC3B mRNA is already upregulated in the in situ stage of breast cancer, which is in line with the high genomic resemblances between DCIS and IBC." (PMID 31357602, 2019). "Recently, it has also been shown that APOBEC3B influences metastasization, prognosis and endocrine therapy resistance in estrogen receptor (ER) -positive breast cancer." (PMID 30093965, 2018). "Overexpression of APOBEC3B in breast cancer cell lines results in DNA fragmentation, increased C>T mutations, delayed cell cycle arrest, and eventual cell death." (PMID 29435122, 2018). "In breast cancer, the C to T transition mutation of TCA or TCT sequences by APOBEC3B has been observed frequently." (PMID 30093965, 2018). "Possible molecular impact of coordinated expression levels of APOBEC3A and APOBEC3B in the breast cancer cell lines analyzed in our study is of interest and requires further investigation." (PMID 29642934, 2018). "Our study showed that APOBEC3B mRNA expression correlated with sensitivity to NAC in breast cancer patients." (PMID 30093965, 2018). "Subgroup analysis by ER-status showed that increased APOBEC3B levels in distant metastases were restricted to metastases arising from ER-positive primary breast cancers (P = 0.002)." (PMID 28141868, 2017). "In primary breast cancer, APOBEC3B mRNA is deregulated in a substantial proportion of cases and its expression is associated with poor prognosis." (PMID 28141868, 2017). "For APOBEC3B, 13 samples were tested: one sample (healthy control) had two copy deletions, ten samples had one copy deletion (4 healthy controls and 6 breast cancer cases) and two samples (breast cancer cases) had diploid copy numbers." (PMID 29116104, 2017). "APOBEC3B thus seems not only needed for breast cancer progression, but also for maintenance of the metastasis in distant environments." (PMID 28141868, 2017). "This suggests a potential role for APOBEC3B in luminal breast cancer progression, and consequently, a promising role for anti-APOBEC3B therapies in advanced stages of this frequent form of breast cancer." (PMID 28141868, 2017). "In conclusion, our findings add to the knowledge that APOBEC3B contributes to breast cancer progression and has now extended this to metastatic disease." (PMID 28141868, 2017). "Recently, several studies showed that APOBEC3B is a common enzymatic mutagenic factor affecting the evolution of different cancer types, including breast cancer." (PMID 28141868, 2017). "APOBEC3B mRNA levels are significantly higher in breast cancer metastases as compared to the corresponding ER-positive primary tumors." (PMID 28141868, 2017). "In this study, we therefore quantified APOBEC3B mRNA in primary breast cancers and paired metastases to gain more insight into the levels of expression during breast cancer progression." (PMID 28141868, 2017). "This suggests that APOBEC3B, at least in part, underlies the APOBEC-driven mutational process in breast cancer, but also in other cancers." (PMID 27552096, 2016). "APOBEC3B contributes to invasive breast cancer mutagenesis and cytosines within TpC dinucleotides have been identified as preferred APOBEC3B deamination targets." (PMID 26926109, 2016).
breast cancer (continued). "Here we took advantage of this signature as readout for DDT at APOBEC3B-induced AP-sites in the genomes of invasive breast cancers." (PMID 26926109, 2016). "To evaluate the predictive value of APOBEC3B copy numbers, we had two cohorts of breast cancer patients available that were treated with first-line therapy for recurrent disease." (PMID 27552096, 2016). "By performing the cytidine deamination assays following depletion of APOBEC3B by RNA interference (RNAi), we confirmed that all detectable hydroxyurea-induced deamination activity in the breast cancer cell lines was attributable to APOBEC3B." (PMID 27634334, 2016). "Analysis of breast cancers from METABRIC revealed breast cancers from APOBEC3B deletion carriers to have significantly higher abundance of tumour-infiltrating immune cells (P < 0.001)." (PMID 27233495, 2016). "In a previous study conducted in a large cohort of breast cancer cases, the APOBEC3B mRNA levels were significantly higher in subjects with a high tumor grade and ER—and PR—tumors." (PMID 27977754, 2016). "In a previous study, we had analyzed APOBEC3B mRNA expression in 1,491 breast cancer patients and found that high APOBEC3B expression had prognostic value and was associated with poor outcome in untreated LNN patients with ER-positive breast cancer." (PMID 27552096, 2016). "This is consistent with previous results using TCGA and METABRIC datasets, where breast cancers arising from predominantly APOBEC3B deletion carriers of European descent were reported to be enriched for immune response-related gene sets." (PMID 27233495, 2016). "In the current study, we examined separately the prognostic and predictive value of APOBEC3B copy number in a total of 1,756 breast cancer patients." (PMID 27552096, 2016). "In collaboration with the group of Drs Martens and Span in the Netherlands, they analysed APOBEC3B levels in tumours samples from patients with recurrent ER+ breast cancer." (PMID 26913069, 2016). "We observed the immune scores to be significantly different across APOBEC3B copy number with A3Bdel/del, A3Bdel/wt, and A3Bwt/wt breast cancers with median immune scores of 1354, 1321 and 1093 (P < 0.001), respectively in breast cancers from METABRIC." (PMID 27233495, 2016). "Meanwhile, a similar trend was observed for TNM stage, with higher APOBEC3B and lower APOBEC3C mRNA level associated with advanced breast cancer stage." (PMID 26682542, 2015). "It is a member of the apolipoprotein B mRNA-editing enzyme, catalytic polypeptide-like editing complex family together with APOBEC3B, which was found to be a source of mutagenesis in many major cancer types, including breast cancer." (PMID 25505134, 2015). "Along with high expression levels of APOBEC3C gene in ER− breast cancer cells, it is possible that both APOBEC3B and APOBEC3C retain DNA cytosine deaminase activity in breast cancer." (PMID 26682542, 2015). "In fact, a recent study with head/neck cancer implicated APOBEC3B mutagenesis in activation of the kinase PIK3CA, which is also mutated in a large proportion of breast cancers." (PMID 25848704, 2015). "show that APOBEC3B is required for the regulation of gene expression by the estrogen receptor in breast cancer cells." (PMID 26411678, 2015).